HRAS (HRas proto-oncogene, GTPase)
Diseases named in the same sentence as HRAS in open-access papers (continued):
Sharing a sentence is not in itself a finding about the gene and the disease.
renal fibrosis (4 papers, 2014 to 2025). A final common manifestation of a wide variety of chronic kidney diseases characterized by glomerulosclerosis and tubulointerstitial fibrosis. "HRAS and the downstream MEK/ERK pathways are activated by unilateral ureteral obstruction (UUO), and KO of HRAS in mice reduces UUO-induced renal fibrosis." (PMID 39913299, 2025). "In our study, we demonstrated that HRAS activated RREB1, enhancing SMAD2/3 association with Snai1 and Has2cis-regulatory regions during renal fibrosis." (PMID 39913299, 2025). "The results showed that in the renal fibrosis models induced by FA and UUO surgery, the palmitoylation levels of HRAS gradually increased." (PMID 39913299, 2025).
salivary gland tumors (4 papers, 2015 to 2024). "PIK3CA mutations were found in 59% of HRAS-mutant salivary gland tumors but due to the limited number of KRAS- and NRAS-mutant tumors of this lineage this was not significantly different, but was more prevalent than in other HRAS-mutant cancers (p<0.05)." (PMID 37503077, 2023). "A considerable percentage of HRAS mutations were present in codon 61, particularly in salivary gland tumors." (PMID 35600380, 2022). "HRAS mutations are more prevalent in oral cavity and salivary gland tumors." (PMID 35600380, 2022). "HRAS mutations were more prevalent in oral cavity and salivary gland tumors." (PMID 35600380, 2022).
thymic carcinoma (4 papers, 2017 to 2025). Thymic carcinoma (TC) is a type of thymic epithelial neoplasm characterized by a high malignant potential.
urothelial hyperplasia (4 papers, 2008 to 2022). Hyperplasia of the transitional epithelium of the urinary tract. "Expression of HRAS with activating mutations in urothelial cells results in superficial tumors and urothelial hyperplasia." (PMID 36430344, 2022). "We recently showed that activation of HRAS proto-oncogene in urothelial cells of transgenic mice causes simple urothelial hyperplasia (SUH) which is persistent and whose transition to low-grade papillary urothelial carcinoma (UC) must undergo nodular urothelial hyperplasia (NUH)." (PMID 26992222, 2016). "Our results indicate that maintenance of urothelial hyperplasia in Upk2-HRAS* mice depends on continuous expression of Foxa1 and activated HRAS, and that mutated receptor tyrosine kinases, FOXA1 and/or other downstream effectors may mediate oncogene addiction in urothelial hyperplasia." (PMID 30670749, 2019).
vascular malformation (4 papers, 2020 to 2025). A non-neoplastic disorder that is the result of defects of vascular morphogenesis. "Vascular malformations contain driver mutations in GNAQ, HRas and phosphoinositol-3 kinase subunits, underlying Sturge-Weber disease, and other vascular malformations." (PMID 32046305, 2020). "Furthermore, atypical variants in some oncogenes are (almost) exclusively found in vascular malformations (e.g. atypical HRAS and KRAS indel variants)." (PMID 38778413, 2024). "And recurrently mutated genes were identified in several vascular malformations as well including TEK/TIE2 mainly in venous malformations, GNA11/14 mainly in vascular tumors, KRAS/NRAS/RASA1/HRAS mainly in AVMs, GNAQ, IDH1/2, AKT1, PTEN and PIK3CA." (PMID 34736485, 2021).
acute myeloid leukemia (3 papers, 2014 to 2025). Acute myeloid leukemia (AML) is a group of neoplasms arising from precursor cells committed to the myeloid cell-line differentiation. "HRAS mutations are thus rarely found in myeloid malignancies, whereas mutations leading to oncogenic KRAS or NRAS activation occur in ~ 40% of cases with chronic myelomonocytic leukemia and in 20% of cases of monocytic (FAB classes M4 and M5) forms of acute myeloid leukemia (AML)." (PMID 30323311, 2019). "Proof-of-concept studies in animal models using the HRas inhibitor tipifarnib, which is already in phase II clinical trials for the treatment of acute myeloid leukemia in elderly patients (NCT01364038), may also open the way for the development of antiviral HRas inhibitors." (PMID 24553110, 2014).
anaplastic thyroid cancer (3 papers, 2021 to 2025). "One is that certain mutations of the RAS genes, notably HRAS codon 13 mutations previously reported in anaplastic thyroid cancer, and KRAS codon 61 in both PTC and PDTC, were not analyzed." (PMID 32638211, 2021).
bladder urothelial carcinoma (3 papers, 2020 to 2025). "Analysis of various public databases revealed that HRAS gene mutation frequency and mRNA expression are higher in bladder urothelial carcinoma." (PMID 33036162, 2020).
chordoma (3 papers, 2014 to 2022). Chordomas are rare malignant tumors arising from embryonic remnants of the notochord in axial skeleton. "In a recent work, a zebrafish model of chordoma has been obtained constitutively expressing the HRAS pathway." (PMID 25071022, 2014). "HRAS mutations have not been reported in human chordomas, and we presume that activation of the proliferative signals might be relatively attenuated in the human disease." (PMID 24311731, 2014).
cutaneous squamous cell carcinoma (3 papers, 2016 to 2024).
depression (3 papers, 2020 to 2024). "Scoring of binding targets revealed that HRAS, MMP9, and Caspase‐3 could be explored as the dominant targets of GAS for depression treatment." (PMID 37650449, 2024).
dysplasia (3 papers, 2010 to 2025). A usually neoplastic transformation of the cell, associated with altered architectural tissue patterns. "Clinical cases have found that elevated levels of fibroblast growth factor 23 in patients with dysplasia are associated with HRAS mutations." (PMID 31781279, 2019).
Intellectual disability (3 papers, 2016 to 2024). "Heterozygous variants of HRAS cause Castello syndrome, characterized by coarse facial features, short stature, heart defects, hypotonia and intellectual disability." (PMID 32779773, 2020). "By exome sequencing, we detected a novel mutation in HRAS gene (NM_005343.2:p.Arg68Trp), present also in the proband’s daughter, who showed mild LVH and severe intellectual disability." (PMID 28002430, 2016).
inverted urothelial papilloma (3 papers, 2015 to 2023). An endophytic lesion in the urinary tract which shares several morphologic features with urothelial papilloma. "The mutations of HRAS were predominant in inverted urothelial papilloma and patients with HRAS mutations have higher protein expression of HRAS." (PMID 37704624, 2023). "Histological subtypes could play a role as a report described a high frequency of HRAS mutations in inverted urothelial papilloma (IUP) - an uncommon neoplasm of the urinary bladder with distinct morphologic features." (PMID 26544513, 2015). "Additionally, through correlation analysis between the protein of HRAS and enriched pathways showed that HRAS protein might suppress mTOR pathway by inhibiting TSC2 ability in inverted urothelial papilloma." (PMID 37704624, 2023).
metastatic colorectal cancer (3 papers, 2018 to 2023). "Approximately 50% of patients with metastatic colorectal cancer has mutations in the RAS gene, including HRAS, KRAS, and NRAS mutations, most of which are KRAS mutations." (PMID 37370699, 2023).
metastatic tumors (3 papers, 2016 to 2024). "According to this study, aberrations in EGFR and KRAS were encountered in both primary and metastatic tumors, while certain mutations such as HRAS could only be traced to metastatic tumors." (PMID 38539567, 2024). "Patient 5 had somatic mutations in HRAS p.G13C, CASP8 p.R127* and PDGFRA p.R764H at all sub-sites in primary and metastatic tumor samples again consistent with these being truncal events." (PMID 27034009, 2016).
triple-negative breast carcinoma (3 papers, 2017 to 2024). An invasive breast carcinoma which is negative for expression of estrogen receptor (ER), progesterone receptor (PR), and human epidermal growth factor receptor 2 (HER2). "It has been reported that HRAS mRNA level has prognostic meaning in triple-negative breast cancers." (PMID 29349077, 2017).
urothelial papilloma (3 papers, 2020 to 2025). A rare benign condition, characterized by a papillary growth in the urinary tract with a central fibrovascular core. "Of them, HRAS mutations have been reported to be the predominant inverted type of urothelial papilloma." (PMID 40227699, 2025). "Therefore, urothelial papilloma shows a higher mutation rate in MPRIP, HRAS, and MAP3K1 genes, whereas papillary UC carries mutations in FGFR3 and PPFIBP1." (PMID 40227699, 2025). "Proteogenomic integration analysis indicates the mutations of HRAS regulated mTOR signaling to form urothelial papilloma rather than papillary urothelial cancer (PUC)." (PMID 37704624, 2023). "HRAS, ALDH7A1, CBLB, and MPRIP proteins are differently expressed in urothelial papilloma and papillary UC." (PMID 40227699, 2025).
uveal melanoma (3 papers, 2005 to 2019). A melanoma derived from melanocytes of the uveal tract. "We thus screened for activating mutations in the NRAS, HRAS, KRAS and BRAF genes in uveal melanoma cell lines and primary uveal melanomas." (PMID 15928660, 2005). "Mutations of NRAS, KRAS, and HRAS occur in 10–25%, 2%, and 1% of non-uveal melanoma, respectively, including those arising both on sun-exposed and sun-unexposed skin, mucosal, and acral melanomas; in contrast, RAS mutations are rarely observed in uveal melanomas." (PMID 30934534, 2019).
adrenal tumors (2 papers, 1998 to 2024). "Contrary to experiences from Europe, Asian patients with PPGL due to PVs in kinase signaling genes NF1, HRAS, and FGFR1 showed a high proportion of sympathetic tumors, while European patients almost exclusively had adrenal tumors (P < .005)." (PMID 38481600, 2024).
alcoholism (2 papers, 2017 to 2019). "Seven nodes including JUN, FOS, RELA, MAPK1, ATF2, HRAS, and CREB1 in the backbone are the recorded genes of alcoholism, amphetamine addiction, or cocaine addiction in the KEGG pathways." (PMID 30899073, 2019).
bladder (2 papers, 2010 to 2018). "In the current study, we presented a comprehensive meta-analysis for 12 polymorphisms in four VEGF/hypoxia/angiogenesis pathway genes (VEGF, HIF1α, eNOS, and HRAS) including 96 case-control studies to examine the precise associations between these polymorphisms and risk of urogenital neoplasms." (PMID 29942264, 2018).
bone tumor (2 papers, 2019 to 2024). "The analysis of IHC staining showed that upregulating MAZ enhanced, while silencing MAZ repressed HRAS and KRAS expression in the bone tumor tissues from tibia in different mice groups, confirming the positive correlation of MAZ with HRAS and KRAS in these PCa cells." (PMID 31488180, 2019).
breast adenocarcinoma (2 papers, 2013 to 2021). "HRAS overexpression is also associated with an anaplastic phenotype in mammary adenocarcinomas." (PMID 23380875, 2013).
cutaneous nevi (2 papers, 2024 to 2025). "​​Nevus sebaceous is considered to be caused by postzygotic mosaic mutations in the HRAS or KRAS genes, leading to somatic mosaicism and activation of pathways such as MAPK and PI3K-AKT, promoting cellular proliferation." (PMID 41322847, 2025).
epidermal nevus (2 papers, 2019 to 2023). "Parallel sequencing identified a gain-of-function variant (c.37G>C, p.Gly13Arg) of HRAS in both epidermal nevus and tumor but not in leukocytes or buccal mucosal epithelial cells, indicating its postzygotic origin." (PMID 37636262, 2023).
esophageal cancer (2 papers, 2015 to 2025). A primary or metastatic malignant neoplasm involving the esophagus. "In esophageal cancer, LEF1 activates the ERK/MAPK signaling pathway via the Id3/HRAS axis, thereby promoting the development and progression of esophageal squamous cell carcinoma (ESCC)." (PMID 40810004, 2025). "Here, we show that mutant HRAS hyperactivates the RAS and the mTOR pathway in various cancer cell lines including lung, bladder and esophageal cancer." (PMID 26544513, 2015).
hypopharyngeal cancer (2 papers, 2012 to 2022). Carcinoma, predominantly squamous cell, arising from the epithelial cells of the hypopharynx. "Using previously published data we compared 67 hypopharyngeal cancers to 595 HNSCC from other sites and found no prominent differences in mutational frequency except for CASP8 and HRAS genes." (PMID 35664801, 2022).
hypophosphatemia (2 papers, 2023 to 2025). Lower than normal levels of phosphates in the circulating blood. "HRAS p.G12V expression in dysplastic skeletal lesions increased circulating FGF23, causing hypophosphatemia and osteomalacia." (PMID 36943390, 2023).
influenza (2 papers, 2005 to 2011). An acute viral infection of the respiratory tract, occurring in isolated cases, in epidemics, or in pandemics; it is caused by serologically different strains of viruses (influenzaviruses) designated A, B, and C, has a 3-day incubation period, and usually lasts for 3 to 10 days. "Inhibiting MLC phosphorylation by blocking RhoA/Rho kinase, phospholipase C/protein kinase C, and HRas/Raf/MEK/ERK pathways with the use of genetic or chemical manipulation leads to the inhibition of influenza proliferation." (PMID 21731751, 2011). "However, in the present study, we showed that activation of HRas, PKC-α, and RhoA are required for influenza-induced ERK phosphorylation." (PMID 21731751, 2011).
invasive breast carcinoma (2 papers, 1992 to 2024). A carcinoma that infiltrates the breast parenchyma. "Additionally, although recent evidence has reported a role for overexpression of wild-type KRAS, HRAS, or NRAS in different carcinomas, including invasive breast cancers, a driver role in their wild-type form for tumorigenesis in in vivo models has not yet been demonstrated." (PMID 38987766, 2024).
left ventricular hypertrophy (2 papers, 2016 to 2020). Enlargement of the LEFT VENTRICLE of the heart. "In conclusion, the present study reports two different mutations in MYH7 and HRAS genes that independently contribute to left ventricular hypertrophy in the same family." (PMID 28002430, 2016). "The ability of mutated HRAS to activate both ERK and ELK1 was intermediate between that of wild type and oncogenic HRAS, suggesting that this constitutional activation drives the cell proliferation in left ventricular hypertrophy." (PMID 28002430, 2016).
medullary carcinoma (2 papers, 2022 to 2024). "Mutations occur in any of the RAS genes (NRAS > HRAS > KRAS in nodules/tumors of follicular cells, HRAS > KRAS > NRAS in medullary carcinoma)." (PMID 38108848, 2024).
medulloblastoma (2 papers, 2008 to 2022). A malignant, invasive embryonal neoplasm arising from the cerebellum. "Expression of the G12V mutation of pro-oncogene HRAS or HRAS (G12V) and V600E mutations of BRAF induced resistance to SMO inhibitors, such as sonidegib, vismodegib, and LEQ-506, in Shh-subtype medulloblastoma (SMB) cells." (PMID 35163655, 2022).
myoepithelioma (2 papers, 2020 to 2022). "A concurrent HRAS mutation identified in salivary mucoepidermoid tumor patient will most likely not respond to a PI3KCA inhibitor, however, the myoepithelioma patient could benefit from off-label therapy." (PMID 32570879, 2020).
neuroendocrine tumors (2 papers, 2022 to 2024). "Moreover, HRAS overexpression in gastroenteropancreatic neuroendocrine tumors is strongly associated with a notable response to lenvatinib." (PMID 38933262, 2024).
pancreatic adenocarcinoma (2 papers, 2021). "Interestingly, components of EFR3A signaling are upregulated in human pancreatic adenocarcinoma, but not other tested RAS-mutant (KRAS, NRAS, or HRAS) cancers." (PMID 34504076, 2021).
phacomatosis pigmentokeratotica (2 papers, 2014 to 2025). "The same was true in phacomatosis pigmentokeratotica because its two components were found to originate from one single pleiotropic HRAS mutation present in a heterozygous state, being now considered as an example of “pseudodidymosis”." (PMID 25506441, 2014).
pituicytoma (2 papers, 2019 to 2021). An extremely rare, WHO grade I, circumscribed and slow-growing tumor that arises from the neurohypophysis or infundibulum and described in adults. "However, an HRAS mutation was seen in a spindle cell oncocytoma, which is likely a morphologic variant of pituicytoma." (PMID 31046843, 2019).
pituitary adenomas (2 papers, 2010 to 2016). "Various MEN1 mutations have been implicated in pituitary adenoma, and pituitary adenomas with HRAS mutations show increased aggressiveness." (PMID 27175596, 2016). "HRAS mutations have been previously associated with increased aggressiveness in pituitary adenomas." (PMID 27175596, 2016).
poorly differentiated thyroid cancer (2 papers, 2024 to 2025). "Additionally, NF2 loss in combination with HRAS mutation leads to murine poorly differentiated thyroid cancer (PDTC)." (PMID 39796693, 2024).
skin papilloma (2 papers, 2011 to 2022). A benign papillary neoplastic growth on the skin composed of epithelial cells and a fibrous stalk. "HRAS mutations are found in skin papillomas and cSCCs and increase in frequency when MAP3K family members are inhibited, suggesting a link between blockade of mitogen-activated protein kinase (MAPK) signaling and initiation of RAS-primed cells." (PMID 35325006, 2022).
spitzoid melanoma (2 papers, 2020 to 2025). "Spitzoid melanomas often necessitate a panel of melanocytic and proliferation markers, with molecular testing (e.g., for Harvey rat sarcoma viral oncogene homolog (HRAS) mutations or anaplastic lymphoma kinase (ALK) fusions) playing a confirmatory role." (PMID 40984902, 2025).
syringocystadenoma papilliferum (2 papers, 2021 to 2025). A benign adnexal neoplasm occurring during childhood or adolescence. "Recently, the genetic mutations of BRAF and HRAS have been reported in SP, considering it to be the salivary complement of benign sweat tumor of skin, syringocystadenoma papilliferum." (PMID 41322839, 2025). "Notably, syringocystadenoma papilliferum of the skin, histologically analogous to SP, also exists BRAF and HRAS mutations, which suggests SP may be considered to be a salivary counterpart of syringocystadenoma papilliferum of the skin." (PMID 33712056, 2021).
vulva carcinoma (2 papers, 2014 to 2021). A primary or metastatic malignant neoplasm involving the vulva. "In the present study, 25 vulvar carcinomas (of which 19 HPV-negative tumours) were analysed, and one PIK3CA, 3 CDKN2A, and 2 HRAS mutations were detected in the HPV-negative carcinomas." (PMID 24671188, 2014). "Although the numbers of vulvar carcinomas included are small, vulvar cancer seems to have a different mutational spectrum as compared to other gynaecological malignancies with CDKN2A (12%) and HRAS (8%) most often affected." (PMID 24671188, 2014).
vulvar cancer (2 papers, 2014 to 2019). "The results of our study prompt further investigation of the roles of HRAS and CDKN2A in vulvar cancer." (PMID 24671188, 2014).
alcoholic liver diseases (1 paper, 2022). A disorder caused by damage to the liver parenchyma due to alcohol consumption. "In addition, ginseng Huang jiu could improve alcoholic liver disease by regulating the GSTP1, HRAS, AKR1B1, GSTA1, Androgen receptor (AR), GSR, and LDHB genes through bioinformatics analysis." (PMID 36034901, 2022).